TRIP13 (thyroid hormone receptor interactor 13)
Diseases named in the same sentence as TRIP13 in open-access papers (continued):
Sharing a sentence is not in itself a finding about the gene and the disease.
tumor (continued). "For instance, TRIP13 contributes to GC cell growth, movement, and penetration in a laboratory setting, along with tumor development and spread in a living organism by stabilizing DDX21 expression." (PMID 41007830, 2025). "Further analysis revealed that elevated TRIP13 protein levels in GC tissues are correlated with tumor depth." (PMID 41007830, 2025). "The effect of TRIP13 knockdown on tumor formation was examined using a subcutaneous xenograft model in nude mice." (PMID 41487520, 2025). "Additional examinations indicated that except for PAAD and THCA, TRIP13 expression levels in tumor tissue samples were considerably higher than those in healthy tissues (P < .01)." (PMID 40441196, 2025). "We also analyzed TRIP13 expression levels in each tumor type and evaluated the pharmacological sensitivity of these 26 drugs." (PMID 40441196, 2025). "IHC analysis exposed elevated TRIP13 protein levels in GC tissues and connected it with tumor depth." (PMID 41007830, 2025). "Following implantation of non-targeting control (shCtrl) and shTRIP13-2 expressing cells, tumor growth was suppressed in the TRIP13 knockdown group." (PMID 41487520, 2025). "Previous studies have established that TRIP13 promotes tumor cell proliferation, metastasis, drug resistance, and glycolysis in various cancers." (PMID 41007830, 2025). "Functional assays demonstrated that two miRNAs acted as tumor-suppressive miRNAs in BC cells by targeting cell-cycle-related genes (e.g., TRIP13, CCNB1, RAD51, PSPH, CENPN, KPNA2, and MXRA5)." (PMID 39728605, 2024). "The AAA+ family ATPase thyroid hormone receptor-interacting protein 13 (TRIP13) has been reported to play an essential role in developing various tumours." (PMID 39187490, 2024). "Decreasing TRIP13 and increasing Mad2 inhibits cell and tumor growth, suggesting TRIP13 inhibition as a potential therapy." (PMID 38914609, 2024). "A decrease in TRIP13 levels leads to lipid droplet accumulation and functional aMTOCs interference with spindle polarity during mitosis, leading to tumour cell death." (PMID 39187490, 2024). "TRIP13 overexpression promotes tumor development, progression, migration, and invasion, underscoring its oncogenic role." (PMID 37432513, 2023). "TRIP13 expression status was significantly subjective to tumor-node-metastasis (TNM) staging and poor survival." (PMID 37432513, 2023). "To further understand the association between TRIP13 protein levels and tumor development, we utilized the TCGA and GSE62232 databases to compare TRIP13 protein levels in HCC liver tissue with normal liver tissue." (PMID 37740123, 2023). "Numerous studies have reported that TRIP13 protein is overexpressed in various types of human cancer, significantly contributing to tumor cell growth, invasion, and metastasis." (PMID 37740123, 2023). "Our IHC results revealed a significantly higher rate of positive TRIP13 expression in tumor tissue, supporting previous findings." (PMID 37740123, 2023). "Regarding miR-139-3p target genes, thyroid hormone receptor interactor 13 (TRIP13) was found to be directly regulated by tumor-suppressive miR-139-3p in LUAD cells." (PMID 38067275, 2023). "The results showed that 52 cases (57.78%) of tumor tissue and 33 cases (42.22%) of paratumor tissue exhibited elevated levels of TRIP13 protein." (PMID 37740123, 2023). "And DFS in HCC patients was affected by the levels of TRIP13 protein, tumor size, number of tumors, TNM stage, and AFP levels (50 g/L versus > 50 g/L) (P < 0.05)." (PMID 37740123, 2023). "Based on this study and previous data, TRIP13 overexpression is partially due to the downregulation of several tumor-suppressive miRNAs in cancer cells." (PMID 38067275, 2023). "IHC analysis revealed decreased Ki67 and TRIP13 staining in tumor sections from mice treated with a combination of MK-2206 and osimertinib, compared with drug alone group." (PMID 37669963, 2023).
tumor (continued). "Subsequently, we validated the TRIP13 expression in HCC using an independent cohort of tumor and paratumor tissue samples obtained from our institution." (PMID 37740123, 2023). "After minute scrutinization of IHC results in various tumor cores, it notifies that the expression of TRIP13 was commonly found in cytoplasm and on the membrane and sometimes in the nucleus." (PMID 38074464, 2023). "For example, TRIP13 was shown to promote cancer cell proliferation and the epithelial-mesenchymal transition in various tumor types, and we identified here a functionally relevant DBS regulating Trip13 expression." (PMID 37661832, 2023). "From the analysis of BC datasets in the Oncomine and UALCAN databases, TRIP13 was found to be highly expressed in BC tumour tissue compared with normal controls, an observation validated by IHC analysis of physical samples from our BC patients." (PMID 35322916, 2022). "In our prior study, we demonstrated the oncogenic role of TRIP13 by evaluating tumour growth and metastasis of CRC." (PMID 35194944, 2022). "For example, previous studies have shown that SHC3 is functionally relevant to TRIP13-mediated tumor growth and metastasis." (PMID 35155682, 2022). "TRIP13 was highly expressed in lung metastatic lesions compared with primary tumours in a 4T1 cell implantation BALB/c mouse model of BC." (PMID 35322916, 2022). "In line with its proposed role as a therapeutic target in various tumor entities, Trip13 knockdown (KD) reduced HCC cell number in vitro with increased apoptosis and DNA damage." (PMID 36031387, 2022). "DCZ0415, a small molecule inhibitor targeting TRIP13, induced anti-tumor activity in vitro and in vivo." (PMID 35075117, 2022). "Recent studies have indicated that thyroid hormone receptor interactor 13 (TRIP13) is abnormally expressed in many tumor tissues and related to poor prognosis." (PMID 35601150, 2022). "Transcription levels of TRIP13 in tumours were initially evaluated using data from the Oncomine database, revealing that TRIP13 was highly expressed in multiple tumours compared with normal samples, including BC." (PMID 35322916, 2022). "Expression of TRIP13 is elevated in tumours compared to the corresponding normal tissue and is positively correlated with poor outcome in multiple types of cancer." (PMID 35821197, 2022). "Upon diminished Trip13 levels, lipid droplets accumulated and acted as functional aMTOCs disturbing spindle polarity during mitosis, which triggered tumor cell death." (PMID 36031387, 2022). "The results showed that high expression of TRIP13 can reduce the ability of nedaplatin to inhibit tumor cell development." (PMID 35601150, 2022). "Following the concept of precision medicine, assessing Plin2 levels will allow for the stratification of tumor responsiveness to specific mitosis‐targeting drugs, including future Trip13 inhibitors as well as clinically established drugs such as paclitaxel." (PMID 36031387, 2022). "Among all the genes reported in the literature with their potential cause in tumor development, CPEB4, APC, TRIP13, EIF2S3, EIF4A1, IFNg, PIK3CA and CTNNB1 have particularly been identified to be a set of potential candidates for tumor development." (PMID 33237662, 2021). "Our findings indicated that HMGA1 promoted tumor progression via elevating TRIP13 transcription and expression." (PMID 33648560, 2021). "As a central protein in MCC inactivation, TRIP13 promotes tumor progression mainly by altering the conformation of the terminal macromolecule." (PMID 33648560, 2021). "In recent years, more and more studies reported the tumor-promotive roles of TRIP13 in many types of tumors, including PCa." (PMID 34307457, 2021). "We observed the up-regulated TRIP13 expression after irradiation in LGG as well as the recurrence of GBM compared to primary tumor." (PMID 34066132, 2021). "TRIP13 was revealed to be amplified in a variety of human cancers, and was concerned with tumor progression." (PMID 32694945, 2020).
tumor (continued). "The consistent upregulation of TRIP13 in CRCs indicated that it is a potential molecular biomarker for tumor aggressiveness and that it is a target for therapy." (PMID 33037736, 2020). "Further, in‐house validation, accomplished by performing qPCR analysis of frozen samples of paired tumor and normal tissues (n = 95) found TRIP13 overexpression in CRCs as compared to matched normal colon." (PMID 33037736, 2020). "There was higher expression of the TRIP13 protein in tumor tissues relative to their matched normal tissues (Wilcoxon P‐values 6.10e−10)." (PMID 33037736, 2020). "Xenograft experiments indicated that the growth rate of tumours and the volume and weight of tumours in TRIP13-knockdown GBM cells were significantly decreased compared with those in the control groups." (PMID 31740732, 2019). "The data indicated that silencing TRIP13 greatly suppressed tumor growth, as shown by reduced tumor sizes and weights in the MHCC97H-shTRIP13 group compared to those in the negative control group." (PMID 31533816, 2019). "Aside from its important role in tumor cell proliferation, TRIP13 was also reported to promote tumor cell migration and invasion." (PMID 31533816, 2019). "Subcutaneous tumorigenesis experiments in mice showed that TRIP13 significantly promoted the growth of tumours in vivo." (PMID 31740732, 2019). "Mice were injected with OCI-MY5 cells transduced with TRIP13-shRNA or scrambled vectors and TRIP13 knockdown mice clearly showed less tumor burden compared to controls." (PMID 31475039, 2019). "The result showed that the protein level of TRIP13 was up-regulated in tumor tissues compared to normal tissues (P < 0.01)." (PMID 30564064, 2018). "Taken together, silencing TRIP13 acts as a tumor suppresser of HCC to inhibit cell proliferation, promote cell apoptosis and decrease cell migration and invasion in vitro and in vivo." (PMID 30564064, 2018). "When mice were transplanted with HepG2 + silencing TRIP13, both weight and volume of tumor showed noticeable attenuations (P < 0.01)." (PMID 30564064, 2018). "Following experiments proved that TRIP13 was associated with the progression of HCC, and that a high expression of TRIP13 was mainly found in progressive and remission stage of tumor tissues and in several HCC cell lines." (PMID 30564064, 2018). "We observed that, tumor size was significantly smaller in the TRIP13-ShRNA mice compared to those controls (p < 0.05)." (PMID 28157697, 2017). "Dox was added into the drinking water 16 days post tumor engraftment to induce TRIP13 knockdown, which was validated from tumor masses." (PMID 28157697, 2017). "TRIP13 is a thyroid receptor interacting protein whose gene shows copy number changes in 68% of 19 early stage NSCLC tumor samples." (PMID 23717685, 2013). "Similar trends for the cell-cycle-associated genes (ASPM, CENPE, TPX2, TRIP13, KIF11, KIF20A) were observed with their distribution in different-grade tumors, with higher expression levels observed as tumor grade increased." (PMID 23506684, 2013). "TRIP13 was markedly overexpressed in OC tissues and positively correlated with higher tumor stage." (PMID 41907269, 2026). "The findings indicated that TRIP13 levels were significantly linked to tumor depth (p = 0.0253), with no notable associations observed for other clinical features." (PMID 41007830, 2025). "The study involved the categorization of individuals with various tumor types into 2 groups based on whether they had high or low levels of TRIP13 methylation." (PMID 40441196, 2025). "Overall, our findings reveal a significant link between TRIP13 expression levels and the proliferation and metabolic activities of cancer cells in GC, reinforcing its possible importance as a critical factor in gastric carcinogenesis and tumor progression." (PMID 41007830, 2025).
tumor (continued). "Furthermore, the subcutaneous tumour formation experiment demonstrated that knocking down TRIP13 significantly reduced the volume, weight, and growth curve of subcutaneous tumours in mice." (PMID 39187490, 2024). "Additionally, in the tumour group overexpressing DDX21 after knocking down TRIP13, the positive rates of DDX21 and Ki67 significantly recovered." (PMID 39187490, 2024). "Immunohistochemical experiments also showed that the positive rates of TRIP13, DDX21, and Ki67 were significantly reduced in the TRIP13 knockdown tumour group, while after rescuing the expression of TRIP13, the positive rates of TRIP13, DDX21, and Ki67 were significantly restored." (PMID 39187490, 2024). "After rescuing TRIP13, the size and weight of subcutaneous tumours in mice partially recovered." (PMID 39187490, 2024). "Here, in our tumor cells which do not harbor TRIP13 mutations, we see that suppression of TRIP13 leads to decreased viability." (PMID 38589567, 2024). "Notably, the expression of TRIP13 mRNA was significantly higher in tumor tissues (n = 374) than in normal liver tissue (n = 50) and paratumoral tissue (n = 50) (P < 0.001)." (PMID 37740123, 2023). "IHC analysis on human PDAC TMAs tumor cores followed the similar trend of TRIP13 expression." (PMID 38074464, 2023). "Moreover, a strong correlation between the level of TRIP13 mRNA expression and the tumor’s T stage as well as the tumor status was observed." (PMID 37740123, 2023). "The downregulation of TRIP13 promoted apoptosis and inhibited tumor growth." (PMID 37432513, 2023). "In addition, TRIP13 also plays roles in tumor progression and the development of chemotherapeutic resistance." (PMID 37432513, 2023). "The human tumor cores also confirmed immuno-reactivity with the TRIP13 MAb." (PMID 38074464, 2023). "This illustrates that TRIP13 exerts a tumor-promoting role in a variety of tumors, but there may be subtle differences in different tumors." (PMID 36268276, 2022). "Thyroid hormone receptor interactor 13 (TRIP13) correlated with tumor progression and prognosis of patients after several rounds of analysis, including weighted gene correlation network analysis (WGCNA), and further chosen for experimental validation in cancer cell lines and patient samples." (PMID 35075117, 2022). "Furthermore, western blot analysis showed increased levels of GZMB in DCZ0415‐treated tumours, validating our initial observation that TRIP13 inhibition increases levels of GZMB, indicating increased T‐cell infiltration." (PMID 35194944, 2022). "Our results in function assays confirmed that TRIP13 indeed promote tumour progression in BC." (PMID 35322916, 2022). "TRIP13 was more highly expressed in tumor lesions than in adjacent normal tissues." (PMID 36268276, 2022). "TRIP13 generally promotes the progression of tumor cells by affecting cell cycle." (PMID 35601150, 2022). "We hypothesized that TRIP13 mediates the progression of BC through the regulation of tumour cell cycle signalling." (PMID 35322916, 2022). "Aberrant expression of TRIP13 may be related to the occurrence and development of tumours, and the up‐regulation of TRIP13 promotes cell proliferation and migration and increases resistance to chemotherapeutic drugs." (PMID 35322916, 2022). "TRIP13 expression was highly correlated with tumour depth (p < 0.001) in BC patients." (PMID 35322916, 2022). "Taken together, these results suggest that TRIP13 promotes tumour development and may serve as a novel and potential diagnostic or therapeutic target in BC." (PMID 35322916, 2022). "Thus, assessment of Plin2 levels enables the stratification of tumor responsiveness to mitosis‐targeting drugs, including clinically approved paclitaxel and Trip13 inhibitors currently under development." (PMID 36031387, 2022).
tumor (continued). "Aberrant TRIP13 expression has been observed in various human cancers and was shown to be related to a malignant phenotype—e.g., excessive cell proliferation, drug resistance, and tumor progression." (PMID 36268276, 2022). "Overall, our findings suggested that circRNA_100146 may display its tumor-promotive roles via modulating miR-615-5p/TRIP13 axis." (PMID 34307457, 2021). "The activation of TRIP13 enhances tumor proliferation and malignancy." (PMID 34066132, 2021). "Furthermore, an inverse relationship was found between circRNA_100146 and miR-615-5p, and knockdown of circRNA_100146 exerted its tumor-suppressive effects at least in part through regulating miR-615-5p to modulate TRIP13 expression." (PMID 34307457, 2021). "High expression of TRIP13 could lead to an increase of aggression, treat-resistant in tumor cells, and enhance the repair of DNA damage." (PMID 32903581, 2020). "Furthermore, xenograft studies demonstrated high expression of TRIP13 contributed to tumor growth and metastasis." (PMID 33037736, 2020). "Collectively, these results manifested that NORAD inhibition could constrain tumor growth in vivo through the miR-495-3p/TRIP13 axis." (PMID 32694945, 2020). "Furthermore, the level of miR-495-3p was increased and the levels of TRIP13 mRNA and protein were reduced in mice tumor tissues of the sh-NORAD group, while this trend was partly abolished in mice tumor tissues of the sh-NORAD + anti-miR-495-3p group." (PMID 32694945, 2020). "The results show that BIRC5, CENPA, KIF4A, DTYMK, PRC1, and TRIP13 have low beta values in tumor." (PMID 32391055, 2020). "Additionally, TRIP13 is elevated in CRCs, compared to normal colonic tissues, and it facilitates tumor growth and progression." (PMID 33037736, 2020). "Furthermore, to determine the effect of TRIP13 on tumor metastasis, we performed histological examination of formalin-fixed, paraffin-embedded lung tissue sections from mice injected with MHCC97H-shRNA cells via the tail vein." (PMID 31533816, 2019). "We assessed the correlation between the TRIP13 expression and clinicopathological parameters, and found that high TRIP13 levels were positively associated with advanced TNM stages (p = 0.029), larger tumor size (p = 0.014), and lower differentiation (p = 0.031)." (PMID 31533816, 2019). "TRIP13 is highly expressed in various human tumours and promotes tumorigenesis." (PMID 31740732, 2019). "Furthermore, immunohistochemical staining suggested that the expression of TRIP13, Ki67 and c-MYC was significantly reduced in TRIP13-knockdown tumours compared with controls, while the expression of FBXW7 was increased." (PMID 31740732, 2019). "This is a new mechanism for TRIP13 to promote tumor metastasis." (PMID 31533816, 2019). "The results also showed that TRIP13 was highly expressed in tumor tissue (p < 0.001)." (PMID 29540729, 2018). "TRIP13 knockdown also suppressed the formation of tumor in vivo." (PMID 30564064, 2018). "The findings showed that silencing TRIP13 could not only significantly inhibit cell viability, migration and invasion and induce cell apoptosis in vitro, but also inhibit the formation of tumor by increasing apoptosis level in vivo." (PMID 30564064, 2018). "It suggests that the Akt inhibitor, which has been used in clinic, may be functional to target TRIP13 related tumor features." (PMID 28157697, 2017). "Furthermore, when we compare the differentially expressed genes between KPT-330 treated cells as compared to cells with TRIP13 suppression, we find several potential tumor suppressors such as MYCT1 and SAMD9, a gene having antiproliferative properties, whose expression increases." (PMID 38589567, 2024). "Thus, TRIP13 can be a crucial player of tumor microenvironment and tumorigenesis." (PMID 38074464, 2023).